IL6 (interleukin 6)
Diseases named in the same sentence as IL6 in open-access papers (continued):
Sharing a sentence is not in itself a finding about the gene and the disease.
COVID-19 (continued). "We also examined the expression of previously reported inflammatory cytokines (TNF, IL6, IL1B, CCL3, CCL4 or CXCL2) produced by circulating monocytes in patients with COVID-19." (PMID 37363730, 2023). "For instance, lung tissue specimens obtained from COVID-19 patients were enriched for cells co-expressing CCR6 and IL17A and also had high levels of IL-6, IL-17A, GM-CSF, and IFNγ found in BALF." (PMID 38179278, 2023). "The research found that IFN-γ enhances IL-6 production in monocytes and involved in the development of ARDS in COVID-19, while IFN signaling is the pathway leading to PD-1/PD-L1 expression." (PMID 37391394, 2023). "The serum IL-6, IL-8, TNF-α, and IL-1β levels were reported to be elevated in hospitalized patients with COVID-19." (PMID 36864432, 2023). "Studies have reported an increase in the plasma levels of IL-6 and TNF-alpha in hospitalized COVID-19 patients." (PMID 37951972, 2023). "According to the results of any previous studies, IL-6 as a potent proinflammatory cytokine can stimulate c-reactive protein (CRP) and has been introduced as a trigger of the cytokine storm in COVID-19." (PMID 37161412, 2023). "Another study has confirmed these data showing that serum levels of several pro-inflammatory mediators such as IL-6, CXCL8 and TNFα and also serum NETs levels are increased in COVID-19 patients (n = 27), compared to healthy subjects (n = 12)." (PMID 36941580, 2023). "The cytokine profile involved in the pathogenesis of lung damage in COVID-19 is similar to that observed in the pathogenesis of joint damage in RA, with IL1, IL6 and TNF-α as key players." (PMID 37564642, 2023). "Maybe these two parameters (higher neutrophil count and NLR), which were proved to be laboratory indicators of severe COVID-19 due to cytokine storm leading to worse outcomes, could be prognostic factors for clinical response to treatment with tocilizumab in patients with high IL-6 concentration." (PMID 37324114, 2023). "In patients with non-COVID-19 ARDS, the persistent elevation of IL-6 levels was a consistent and efficient predictor of the outcome over time." (PMID 36675573, 2023). "This study revealed that increased IL-6 is associated with long COVID-19; however, the study could not assess from the current available data whether there are differences in such an association according to sex and age or whether it would be affected by a specific comorbidity." (PMID 37095536, 2023). "From our hypothesis, it can be noted that IL-6 represents an essential cytokine that promotes a cascade of events favoring SARS-CoV-2 pathogenesis, as interleukin-6 (IL-6) serum levels were linked to the severity of clinical symptoms and poor COVID-19 prognosis." (PMID 37759738, 2023). "Among all COVID-19 patients, significantly higher levels of IFN-α, IL-6, or TNF-α were shown in serum samples from the Hispanic patients compared with those from the Chinese patients." (PMID 36810114, 2023). "Of note was that for six markers (CRP, ferritin, IL-6, IP-10, SAA1/A2, and S100A12) higher values were detected in COVID-19 sera whereas for ApoA1, significantly lower levels were detected in the COVID-19 group (p<0 · 0001)." (PMID 36590898, 2023). "It has also be shown that elevated concentration of IL-6 not only in GCF was observed, but also in serum —as it was measured in COVID-19 positive patients admitted to the hospital." (PMID 37608339, 2023). "Through stimulation with the recombinant SARS-CoV-2 S protein in whole blood, we identified a signature for COVID-19 based on the cytokines IFN-γ, IL-2, IP-10, IL-1β, IL-6, IL-8, and TNF." (PMID 37018291, 2023). "We found that cells previously exposed to PM10 have a higher production of IL-6 in response to SARS-CoV-2 compared to cells only exposed to the virus, suggesting that PM10 can potentiate the inflammatory response during COVID-19." (PMID 37180105, 2023).
COVID-19 (continued). "The cytokine levels of IL-2, IL-6, IL-7, G-CSF, IP10, MCP1, MIP1A, and TNF-α are determined and were mostly found to be elevated in severe COVID-19 patients with ARDS development related to lung damage and tissue fibrosis." (PMID 36901868, 2023). "Consistent with previous reports on expression of cytokines in serum, we found that expression of IL6 and TGF-β was higher in EVs from COVID-19 patients." (PMID 37251406, 2023). "In this study, we show that C1q or C4BP l plays a role in reducing IL-6 mRNA levels, thereby preventing the progression of SARS-CoV-2 infection to a severe form of COVID-19." (PMID 37376569, 2023). "With initial cases demonstrating remarkable clinical improvements in individuals treated with the anti-interleukin (IL-6) biologic tocilizumab (the standard treatment for CRS), the idea of a CSS in severe COVID-19 became more visible." (PMID 37153613, 2023). "We found that the levels of IL-4, IL-6, IL-8, IL-12, TGF-β, and TNF-ɑ related pathways were upregulated in COVID-19 brains compared with control brains." (PMID 36609561, 2023). "Early reports of COVID-19 showed elevated levels of pro-inflammatory cytokines, e.g., IL1b, TNF and IL6, especially among severe COVID-19 cases, implicating a cytokine-storm process." (PMID 36829233, 2023). "COVID-19 provokes a cytokine immune response, activating Th1 cells and CD14+ and CD16+ monocytes, resulting in a cytokine storm characterized by elevated IL-6, TNF-α, and other cytokine levels." (PMID 38131885, 2023). "IL-6 inhibitors are strongly recommended by the WHO and National Institute for Health and Care Excellence (NICE) in COVID-19 patients either prescribed alone or with corticosteroids." (PMID 38155729, 2023). "Current pharmacotherapy for COVID-19 targets these immune mechanisms via the routine use immunomodulatory therapy (glucocorticoids, IL6 inhibitors and JAK inhibitors in severe to critical cases of COVID-19)." (PMID 37398658, 2023). "In the present study, we reported the clinical manifestations and inflammatory markers including cytokines (IL-6, IL-1β, and TNF-α) in 35 Turkish children with PCR-positive COVID-19." (PMID 37034144, 2023). "In COVID-19 patients who had AKI, IL-6 levels were significantly higher compared with those who did not have AKI." (PMID 38203482, 2023). "As in previous studies, we found increased serum levels of IP-10, IL-1β, IL-6, and IFN-λ2/-3 in patients with MIS-C and in patients with severe COVID-19 compared with controls." (PMID 36282598, 2023). "It is known that COVID-19 raises inflammatory markers like d-dimer, fibrinogen, IL-6, and CRP, especially in severe cases, which are considered good indicators for severity and recovery of COVID-19." (PMID 36508011, 2023). "We found significant elevation of pro-inflammatory-cytokines, including IP-10, IL-6, IL-8, IL-1RA, MIP-1α/β, and MCP-1 in COVID-19 acute necrotizing encephalopathy patients." (PMID 37848421, 2023). "We aimed to determine the ability of inflammatory biomarkers (Il-6, PCT, CRP, and leukocytes) to predict mortality in COVID-19 patients in the ICU." (PMID 37311846, 2023). "In this prospective study, we assessed biomarkers of inflammation (IL-6 and SAA) from the serum of 120 COVID-19 patients, of whom 70 had chronic kidney disease." (PMID 38203482, 2023). "In our data, 61.8% of the pediatric ischemic stroke with COVID-19 cases have concomitant elevation of inflammatory markers (i.e., ESR, CRP, IL-6, fibrinogen, ferritin, procalcitonin and D-dimer)." (PMID 41541110, 2023). "By inactivating interleukin 6 (IL6), HOCl possibly downregulates mediators of the ‘cytokine storm’ that characterizes clinical deterioration in specific diseases (e.g., COVID-19)." (PMID 37034111, 2023). "It is important to conduct research to analyze these three parameters to establish the role of increased IL-6, AKI, and ARDS on COVID-19 mortality in children." (PMID 37889917, 2023).
COVID-19 (continued). "CRP was negatively correlated with IL-6 (r = −0.553, p = 0.011) and positively correlated with MCP-1 (r = 0.389, p = 0.019) in the post-COVID-19 patients." (PMID 37896963, 2023). "In severe COVID-19, inflammatory monocyte signatures predominate and delayed or impaired type I interferon (IFN) production contribute to increased levels of IL-6 and subsequent cytokine storm." (PMID 37425266, 2023). "The levels of many proinflammatory cytokines (IL-1β, IL-6, IL-8, IL-17, TNF, G-CSF, GM-CSF) and chemokines (IP10, MCP1, MIP1α), were elevated in COVID-19 patients, with higher levels in critically ill subjects." (PMID 36672688, 2023). "Age, urea, uric acid, ferritin, IL6, LDH, and CRP-based predictive probability algorithm calculating COVID-19 severity was found to be highly predictive of ICU admission for COVID-19 patients." (PMID 36819455, 2023). "Although LMWH has shown to have a marked capability of decreasing hyperinflammatory state and IL-6 levels, multiple studies displayed different therapeutic and prophylactic effects of LMWH in COVID-19 patients." (PMID 37180701, 2023). "The analysis of our case series confirmed the prominent role of IL-6 levels in response to SARS-CoV-2 infection, as predictors not only of COVID-19 disease severity and unfavorable outcomes, but also long COVID development trends." (PMID 36675242, 2023). "In a small cohort of seven MIS-C patients, differentiation between COVID-19 and MIS-C patients was achieved using a combination of IL-10, IL-1RA, IL-18, IL-6, TNF and IFN-gamma." (PMID 37685502, 2023). "We investigated the serum levels of angiopoietins, as well as interleukin-6 levels and anti-SARS-CoV2 IgG titers, in hospitalized COVID-19 patients across disease severity and healthy controls." (PMID 38138084, 2023). "We detected an increase in the relative expression of the IL-6, CRP, ACE2 and IL-1β biomarkers of 2 mild cases and one moderate case with long COVID-19 compared to healthy individuals." (PMID 37715121, 2023). "In multiple studies exploring routine laboratory parameters in COVID-19 patients, increased CRP levels and IL-6 were also reported in severe patients when compared to non-severe patients." (PMID 37624796, 2023). "With a sensitivity of 92% and a specificity of 65–67%, IL-6 ≥ 52.8 pg/ml, PCT ≥ 0.11 ng/ml, and CRP ≥ 71.1 mg/L were predictive of a severe course of COVID-19." (PMID 37937220, 2023). "Our data agree with another study that verified inflammatory profiles in COVID-19, demonstrating increases in serum levels of IL-1β, IL-6, IL-8, and TNF in patients with COVID-19 compared to healthy donors." (PMID 37018291, 2023). "In COVID-19, patients with confirmed bacterial infections, blood level of neutrophils, CRP, ferritin, IL-1β, IL-2R, IL-6, and TNF-α were higher than the upper limits of the normal values with significant differences, while lymphocyte was significantly lower." (PMID 37771749, 2023). "COVID-19 patients showed significant correlations (all p < 0.01) of hs-CRP with IL8 (r = 0.421), MCP3 (r = 0.660), CXCL10 (r = 0.391), CCL23 (r = 0.555), and IL6 (r = 0.687)." (PMID 37832397, 2023). "The death of some COVID-19 patients is strongly related to cytokine release syndrome (CRS), this is similar to septic patients characterized by excessive IL6, TNFA, IL1B, and CXCL8 levels in their blood." (PMID 36798115, 2023). "It has been reported that inflammatory factors and chemokines (IL-1, IL-6, IL-8, and TNF-α) are elevated in COVID-19 patients." (PMID 37680629, 2023). "Amongst the proinflammatory cytokines found in COVID-19 patients and casualties, the expression of TNF-α and IL-6 outdoes that of their counterparts." (PMID 37047115, 2023). "DPP3 showed a significant and positive correlation with IL-6 (ρ = 0.50, p < 0.001), CRP (ρ = 0.46, p < 0.001), and leucocytes (ρ = 0.20, p < 0.05) in COVID-19 patients." (PMID 37733154, 2023).
COVID-19 (continued). "Overall, higher IL-1β, IL-6, and TNF- α levels were reported in COVID-19-infected patients compared to patients with periodontitis." (PMID 37106750, 2023). "IgG, IL-6, CRP, NLR, PLR, glucose, AST, urea, creatinine, and eGFR were significantly higher in severe/critical COVID-19 patients." (PMID 36838284, 2023). "SARS-CoV-2 infection triggers extensive production of pro-inflammatory molecules such as CRP, TNF-α, IL-1β, IL-6, MIP-1α, IP-10 and IL-10 by activated inflammatory monocytes and neutrophils recruited into the lungs of COVID-19 patients." (PMID 37854602, 2023). "On top of that, comparing TNF-α and IL-6, the level of TNF-α has been consistently higher in severe COVID-19 patients and those who suffer from comorbidities such as obesity, hypertension, and chronic heart failure." (PMID 37047115, 2023). "EREG has been identified as a critical mediator of IL-6/IL-17-induced upregulation of several EGF members and has been previously identified in COVID-19 as a correlate of inflammation." (PMID 37452024, 2023). "One critical aspect of COVID-19 pathology is the cytokine storm, characterized by an excessive release of proinflammatory cytokines and chemokines like TNF-α, IL-1β, and IL-6." (PMID 37834246, 2023). "The study also measured proinflammatory cytokines and chemokines in the semen, including IL-6, tumor-necrosis-factor (TNF), and CCL2 (MCP-1), and COVID-19 patients had significantly higher levels than the control group." (PMID 37457430, 2023). "IL-6 and IP-10 seemed promising biomarkers successfully discriminating TB from LTBI and COVID-19 from healthy controls." (PMID 36590898, 2023). "We found that increased levels of Ang-II induced increased expression of the cytokines: IL-6, IL-10, IL-33, IL-28A and CD40L in the severe COVID-19 group." (PMID 38137381, 2023). "The up-regulated cytokines (IFN-γ, TNF-α, IL-6, IL-10) in our study indicate induced activation of immune responses against SARS-COV-2 infection and are consistent with other COVID-19 studies." (PMID 38057707, 2023). "Interestingly, recent improvements in the pathophysiologic understanding of COVID-19 revealed that the severity of COVID-19 is strongly associated with cytokine release syndrome (CRS), which is characterized by elevated tumor necrosis factor (TNF-α), interleukin (IL)-6, IL-2, IL-7, and IL-10." (PMID 36770606, 2023). "Compared with the control group, there was extensive cytokine/chemokine correlations centered on IL-17A, IL-10, IL-6, CCL2, CXCL8, CXCL9 and CXCL10 and fewer correlations with IL-1β in the COVID-19 patients at baseline." (PMID 37662953, 2023). "The top three Meliae cortex’s key active phytonutrients were further analyzed for molecular docking with the top ten anti-COVID-19 core targets, including AKT1, TNF, HSP90AA1, IL-6, mTOR, EGFR, CASP3, HIF1A, MAPK3, and MAPK1." (PMID 36817449, 2023). "Specifically, they found that COVID-19 patients with lower SDNN had a worse prognosis, including fewer survival days (p = 0.046), and higher HFnorm was correlated with higher IL-6 levels (p = 0.020)." (PMID 36673664, 2023). "The differentiation of CD4+ T cells, activated by the interaction of IL-23 with TYK2/Jak2, occurs with the participation of IL-6, IL-1β and TGF-β, which is extremely important in the context of the cytokine storm in COVID-19." (PMID 37896870, 2023). "During hospitalization, 12 severe/critical patients with COVID-19 developed multisystem inflammatory syndrome (MIS), which was characterized by elevated inflammatory markers such as CRP, IL-6, and PCT, and the majority of the cases had lymphopenia." (PMID 38274442, 2023). "This evidence is suggestive that IL-6 is not causal and should be taken in the context that variants that alter IL-6 signaling do alter both the incidence and outcomes of other infections and that the trial evidence of IL-6 inhibition has supported the genetic evidence in COVID-19." (PMID 36801374, 2023).
COVID-19 (continued). "Early evidence indicated that the pathogenesis of COVID-19 evoked ARDS is, at least partially, mediated by hyperinflammatory cytokine storm in which interleukin 6 (IL-6) plays an essential role." (PMID 36791125, 2023). "Immunomodulators such as the anti-IL-6 antibody and JAK inhibitors have been shown to improve the survival of hospitalized COVID-19 patients." (PMID 37193781, 2023). "On the other hand, eight out of ten anti-COVID-19 core targets (TNF, EGFR, CASP3, AKT1, MAPK1, MAPK3, mTOR, and IL-6) followed the human cytomegalovirus infection." (PMID 36817449, 2023). "According to the literature data, cytokines IL-1, IL-6, IL-8 and TNF-α participate in immune response in patients with COVID-19." (PMID 37895467, 2023). "COVID-19 progression involves pulmonary hyper-inflammation and release of pro-inflammatory cytokines (e.g., TNF-α, IL-6, IL-1, IL-8, and MCP-1), as part of “cytokine storms”." (PMID 36825200, 2023). "In this study we found persistent elevation of multiple mediators – IL-6, TNFα, SAA, Tie-2, Flt1, PIGF, and CRP – and persistent depression of IL-7 and bFGF in patients recovering from COVID-19 several months following their acute infection." (PMID 36844209, 2023). "We treated purified total monocytes from uninfected and convalescent COVID-19 subjects with LPS and measured TNF-α and IL-6 production by ELISA." (PMID 38250080, 2023). "The antiviral IFN-α and proinflammatory TNF, IL-6, IL-8, IL-17, IL-33, and IFN-γ were elevated in COVID-19 patients at both time points, while IL-10 and IL-1β were increased at admission and one week later, respectively." (PMID 37174682, 2023). "Patients with critical and severe COVID-19 had significantly higher serum concentrations of CRP and IL-6, glucose, urea, AST, LDH and CK at the time of admission." (PMID 37893159, 2023). "In the present study, age (>58), urea (>34), CRP (>71.5), ferritin (>371), IL-6 (>6.4), and LDH (>391) showed the highest odds of predicting ICU admission amongst all other parameters in COVID-19 patients." (PMID 36819455, 2023). "Many studies have observed a general phenotype of elevated IL-6, IL-8, IL-10, and TNF in COVID-19 patients." (PMID 36769761, 2023). "Interestingly, high levels of IgG against the N protein at the time of hospital admission have been correlated with worsened COVID-19 clinical courses, which could be attributed to increased interleukin 6 production mediated by N-specific IgG antibodies observed after COVID-19 cytokine storm." (PMID 37572355, 2023). "For example, a positive correlation was found between lungs and peripheral inflammation in relation to IL-6 (r = 0.53, p < 0.01) and CXCL-10 (r2 = 0.99, p < 0.0001) levels in COVID-19." (PMID 37632046, 2023). "Recent studies have indicated that IL-6 and CRP can be used to assess COVID-19 disease progression and prognosis." (PMID 37894092, 2023). "Patients with mild/moderate illness showed significantly higher expression levels of IL-6, IL-1β, IL-10, CRP and IDO1 than COVID-19-free subjects." (PMID 37715121, 2023). "Nevertheless, we observed that circulating IL-6 and IL-10 values were associated with alterations of redox balance in patients with severe COVID-19, but not in typical ARDS, supporting the hypothesis that oxidative stress enhances the inflammatory response in the progression of SARS-CoV-2 infection." (PMID 37408073, 2023). "Compared with the moderate COVID-19 group, patients with mild COVID-19 were younger, had a shorter dialysis vintage, a lower prevalence of DM, CAD, or TB, lower IL-6 and PCT levels, and higher post-infection albumin level (p < .05)." (PMID 37501590, 2023). "Along with the upregulation of inflammatory mediators such as IL1B, TNF, and IL6, the downregulation of CCL5 can be a major contributor to COVID-19-mediated neuroinflammation." (PMID 37686360, 2023). "The data shows that cytokines like IL-6, TNF-a, and IL-1β are produced by both the influenza virus and SARS-CoV-2, though levels are higher in COVID-19 patients." (PMID 37200377, 2023).